DERL1 (derlin 1)
Diseases named in the same sentence as DERL1 in open-access papers (continued):
Sharing a sentence is not in itself a finding about the gene and the disease.
bladder cancer (6 papers, 2016 to 2025). "Taken together, our results demonstrated that Derlin-1 was overexpressed in bladder cancer and was associated with the malignancy of bladder cancer." (PMID 27977784, 2016). "The next question to be addressed was whether expression of Derlin-1 was associated with clinical outcomes in bladder cancer." (PMID 27977784, 2016). "In patients with bladder cancer, the positive Derlin-1 expression rate was 73.5% in muscle invasive urothelial carcinoma and 47.8% in non-invasive urothelial carcinoma." (PMID 35205628, 2022). "In this study, we identify elevated expression of Derlin-1 in bladder cancer tissues and cell lines, especially in MIBC." (PMID 28178653, 2017). "Using MMP-2/9 antibodies and ERK inhibitor PD98059, we validate that Derlin-1 induces bladder cancer invasion through activation of ERK signaling, which in turn upregulates MMP-2 and MMP-9 protein expression." (PMID 28178653, 2017). "We overexpressed and depleted Derlin-1 in bladder cancer cell lines and examined its roles on cell proliferation, invasion and chemoresistance." (PMID 28178653, 2017). "In conclusion, our study demonstrated that Derlin-1 is overexpressed in bladder cancer and promotes malignant phenotype through ERK/MMP and PI3K/AKT/Bcl-2 signaling pathway." (PMID 28178653, 2017). "In order to investigate the potential mechanism of Derlin-1 induced bladder cancer cell invasion, we checked the expression of invasion related proteins." (PMID 28178653, 2017). "Since Bcl-2 was the target of AKT signaling pathway, we checked the change of AKT activity and found that Derlin-1 positively modulate AKT phosphorylation in bladder cancer cells." (PMID 28178653, 2017). "Our findings link Derlin-1 with EGFR/ERK/MMP signaling and cancer invasion, which contributes to the understanding regarding mechanism of Derlin-1 in bladder cancer progression." (PMID 28178653, 2017). "Derlin-1 depletion significantly upregulated cisplatin-induced apoptosis in 5637 and T24 cells, demonstrating that Derlin-1 confers chemoresistance in bladder cancer cells." (PMID 28178653, 2017). "Here, using MTT cell viability assay and AnnexinV/PI analysis, we demonstrate that Derlin-1 confers cisplatin resistance and reduced apoptosis in bladder cancer cell lines." (PMID 28178653, 2017). "In conclusion, our results provide evidence that Derlin-1 is overexpressed in bladder cancer and that high expression levels of Derlin-1 correlate with tumor grade, metastasis, and poor overall survival." (PMID 27977784, 2016). "Following bioinformatics analysis and assessments by qRT-PCR and western blotting, Derlin-1 was selected as a candidate protein and was then validated in samples from patients with bladder cancer by immunohistochemistry and western blotting." (PMID 27977784, 2016). "The results showed that the bladder cancer tissues exhibited higher levels of Derlin-1 expression than the paracancerous tissues (P < 0.05)." (PMID 27977784, 2016). "The specificity of the primary antibody against human Derlin-1 was validated by IHC staining in TMAs of bladder cancer tissues and paracancerous tissues." (PMID 27977784, 2016). "In addition to its biological effects in promoting the proliferation and invasion of bladder cancer, the high expression of Derlin-1 can also induce bladder cancer cells to become resistant to cisplatin via the PI3K/AKT and MMP/ERK pathways." (PMID 34136492, 2021). "Positive cytoplasmic Derlin-1 staining was observed in bladder cancer tissues." (PMID 28178653, 2017). "Derlin-1 overexpression was observed in 58 of 150 (38.6%) bladder cancer tissues examined." (PMID 28178653, 2017). "We examined Derlin-1 protein expression in 150 cases of bladder cancer tissues." (PMID 28178653, 2017). "Derlin-1 contributes to bladder cancer cell invasion through ERK/MMP signaling pathway." (PMID 28178653, 2017).
bladder cancer (continued). "To determine whether Derlin-1 induced drug resistance involves PI3K/AKT activation, we examined whether treatment with the PI3K/AKT inhibitor LY294005 suppressed vialility of Derlin-1-overexpressing bladder cancer cells in response to cisplatin." (PMID 28178653, 2017). "In this study, we examined Derlin-1 protein expression in 150 cases of bladder cancer specimens." (PMID 28178653, 2017). "We demonstrate that Derlin-1 induces bladder cancer invasion through ERK/MMP signaling." (PMID 28178653, 2017). "Furthermore, the western blotting results showed that Derlin-1 expression in bladder cancer tissue was significantly higher than that in paracancerous tissues at the protein level (all P < 0.05), which is consistent with the immunohistochemical data." (PMID 27977784, 2016). "Further studies are needed to elucidate whether the expression of Derlin-1 is indicative of malignant phenotypes of bladder cancer." (PMID 27977784, 2016). "In addition, Derlin-1 was much more highly expressed in invasive cancer than that in noninvasive cancer tissues, indicating that Derlin-1 was potentially involved in the progression of bladder cancer." (PMID 27977784, 2016). "Lowering the expression of Derlin-1 could re-sensitize bladder cancer to cisplatin." (PMID 34136492, 2021). "The relationship between derlin-1 and bladder cancer chemoresistance also remains unclear." (PMID 28178653, 2017). "We also noticed that PD98059 treatment could induce Derlin-1 protein in bladder cancer cells." (PMID 28178653, 2017). "A limitation of the present study is that it involved only correlative observations of the relationship between Derlin-1 expression and clinicopathological parameters in bladder cancer and lacked direct evidence regarding the function and underlying mechanism of the effects of Derlin-1." (PMID 27977784, 2016). "However, little is known about the role of Derlin-1 in progression of bladder cancer." (PMID 27977784, 2016). "Our results show that expression of Derlin-1 protein was up-regulated in bladder cancer tissues, which is consistent with the expression pattern demonstrated by immunohistochemical analysis, suggesting that up-regulation of Derlin-1 plays an important role in bladder cancer." (PMID 27977784, 2016). "Endogenous expression of Derlin-1 was examined by western blot and realtime RT-PCR in normal bladder transitional epithelial cell line SV-HUC-1 and bladder cancer cell lines." (PMID 28178653, 2017). "Derlin-1 and PI3K p110α co-immunoprecipitated with each other in bladder cancer cells." (PMID 28178653, 2017). "Immunohistochemistry showed that non-neoplastic bladder urothelium was negative for Derlin-1 protein, while Derlin-1 was upregulated in 58 of 150 bladder cancer specimens and correlated with muscle invasive phenotype (T2-T4)." (PMID 28178653, 2017).
cervical cancer (5 papers, 2019 to 2025). A primary or metastatic malignant neoplasm involving the cervix. "Notably, Derlin 1 is overexpressed in various cancer types, including cervical carcinoma, and its presence is closely associated with tumor development and progression." (PMID 40771905, 2025). "In the cervical cancer model, the target gene to be silenced was Derlin-1, an ER membrane protein responsible for transportation of unfolded or misfolded proteins from ER lumen to cytoplasm." (PMID 36430214, 2022). "Derlin-1 is overexpressed in many cancers, including cervical cancer, and its expression is closely related to the migration and development of tumors." (PMID 36430214, 2022).
lung carcinoma (5 papers, 2014 to 2023). "To date, many reports have shown that Derlin-1 overexpression is associated with aggressive phenotype in various cancers including breast, pancreatic and lung cancer." (PMID 28903408, 2017). "Similarly, PKP2 (Plakophilin 2) and DERL1 (Derlin 1) are overexpressed in lung cancer cells, promote the development of lung cancer, and are associated with lung cancer prognosis." (PMID 37328788, 2023). "First, we detected the expression of Derlin-1 in various lung cancer cells, including small lung cancer cells and non-small lung cancer cells." (PMID 24944523, 2014). "Our results show that the expression of Derlin-1 was higher in most non-small lung cancer cells than that in small lung cancer cells, especially in highly metastatic lung cancer cell line 95-D." (PMID 24944523, 2014). "Derlin-1 expression is elevated in breast and lung cancers, and correlated with tumour grade and lymph node metastasis." (PMID 24944523, 2014). "In this study, we explored the effect of Derlin-1 on autophagy-related genes under ER stress in lung cancer cells." (PMID 24944523, 2014). "In addition, Derlin-1 is obviously upregulated in human lung cancer cells, and the inhibition of Derlin-1 attenuates p62 degradation, which leads to the blockage of tumor cell autophagy." (PMID 28219405, 2017). "In addition, we checked EGFR status and found that Derlin-1 overexpression could upregulate EGFR phosphorylation, which was in accord with our previous findings in lung cancer." (PMID 28178653, 2017). "We detected Derlin-1 expression in various lung cancer cell lines, namely, adenocarcinoma cell line A549, LTEP-a-2, Calu-3, GLC-82, large cell lung cancer cell line NCI-N460, small lung cancer cell line NCI-H209, NCI-H446 and highly metastatic lung cancer cell line 95-D." (PMID 24944523, 2014).
amyotrophic lateral sclerosis (4 papers, 2013 to 2024). Amyotrophic lateral sclerosis (ALS) is a neurodegenerative disease characterized by progressive muscular paralysis reflecting degeneration of motor neurons in the primary motor cortex, corticospinal tracts, brainstem and spinal cord. "We have previously shown that the interaction of Derlin-1 with amyotrophic lateral sclerosis (ALS)-associated superoxide dismutase 1 (SOD1) mutants leads to pathological UPR and motor neuron dysfunction." (PMID 39080439, 2024). "Another protein that has been shown to interact with DERL1 is the mutated superoxide dismutase 1 (SOD1), which accumulates and misfolds in motor neurons in amyotrophic lateral sclerosis, another neurodegenerative disease, and the interaction with DERL1 is involved in the disease pathophysiology." (PMID 37936684, 2023).
esophageal squamous cell carcinoma (3 papers, 2017 to 2021). Esophageal squamous cell carcinoma (ESCC) is a type of esophageal carcinoma (EC) that can affect any part of the esophagus, but is usually located in the upper or middle third. "There was one report identifying microRNA-181d as a tumor suppressor in human esophageal squamous cell carcinoma by downregulating Derlin-1." (PMID 28903408, 2017). "Derlin-1 overexpression was observed in 60 of 125 esophageal squamous cell carcinoma tissues." (PMID 28903408, 2017). "We examined Derlin-1 protein in 125 cases of esophageal squamous cell carcinoma (ESCC) tissues." (PMID 28903408, 2017).
lymph node metastasis (3 papers, 2008 to 2025). "Significant associations were observed between Derlin-1 expression and lymph node metastasis, indicateing that Derlin-1 may be associated with aggressive tumor growth or metastasis." (PMID 27977784, 2016). "Recent studies have shown that Derlin-1 expression correlates with tumor grade and lymph node metastasis in different types of malignant tumors." (PMID 27977784, 2016). "The correlations between Derlin-1 expression and a series of clinicopathological characteristics, including age, gender, tumor stage, histological grade, and lymph node metastasis, were determined." (PMID 27977784, 2016). "Increased expression of Derlin-1 was significantly correlated with tumor stage (P < 0.005), histological grade (P < 0.001), and lymph node metastasis (P < 0.001), but not with the patient age (P = 0.758) and gender (P = 0.831)." (PMID 27977784, 2016). "Positive expression of Derlin-1 was significantly correlated with tumor stage, histological grade, and lymph node metastasis (P < 0.001) but was not correlated with other clinicopathological parameters including patient age (P = 0.758) and gender (P = 0.831)." (PMID 27977784, 2016).
non-small cell lung carcinoma (3 papers, 2017 to 2022). A group of at least three distinct histological types of lung cancer, including non-small cell squamous cell carcinoma, adenocarcinoma, and large cell carcinoma. "This target gene encoding Derlin-1 has been detected over-expressed in multiple cancers, including breast, colon, and non-small cell lung cancer." (PMID 29207666, 2017). "The role of miRNA in the molecular pathway in non-small cell lung cancer has been investigated by negatively regulating Derlin-1." (PMID 35205628, 2022). "In non-small cell lung carcinoma, Derlin-1 may also promote cancer cell invasion through the ERK/MMP pathway." (PMID 35205628, 2022).
schizophrenia (3 papers, 2018 to 2022). A major psychotic disorder characterized by abnormalities in the perception or expression of reality. "On the other hand, the hub gene DERL1 is hypomethylated in schizophrenia but with a higher gene expression." (PMID 35386517, 2022).
adenocarcinoma of the colon (2 papers, 2022). "In vitro, emerging researchers have suggested Derlin-1 might promote human cancer cell proliferation and migration, including adenocarcinoma of the colon, hepatocellular cancer, and head and neck cancer." (PMID 35205628, 2022).
bladder tumor (2 papers, 2016 to 2021). "Derlin-1 also promoted chemoresistance through activation of PI3K/AKT/Bcl-2 axis in bladder tumor cells." (PMID 37303943, 2021). "There was Derlin-1 upregulation in bladder tumor tissues and cells." (PMID 37303943, 2021). "Therefore, based on our study, we speculate that Derlin-1 expression may protect cancer cells from stresses encountered during bladder tumor growth." (PMID 27977784, 2016).
Brain atrophy (2 papers, 2021 to 2022). Partial or complete wasting (loss) of brain tissue that was once present. "Both Derlin-1- and Derlin-2-deficient mice exhibited widespread postnatal brain atrophy, which was particularly severe in the cerebellum and striatum." (PMID 34355142, 2021). "Although we cannot exclude the possibility that brain atrophy depends on body growth inhibition, there might be another mechanism by which CNS-specific Derlin-1 or Derlin-2 deficiency induces brain atrophy." (PMID 34355142, 2021). "However, we found that neuron-specific Derlin-1 deletion alone induced brain atrophy and motor dysfunction." (PMID 34355142, 2021). "However, we suggest that an ER stress response triggered by impaired ER quality control does not contribute to the observed postnatal brain atrophy in Derlin-deficient mice because the treatment of primary Derlin-1-deficient neurons with 4-PBA did not mitigate the shortened neurite outgrowth." (PMID 34355142, 2021).
chronic lymphocytic leukemia (2 papers, 2017 to 2022). "Earlier study showed that Derlin-1 was involved in the TCL1-mediated contribution to progression of chronic lymphocytic leukemia in mice." (PMID 28219405, 2017).
hepatocellular carcinoma (2 papers, 2022 to 2025). A malignant tumor that arises from hepatocytes. "In patients with hepatocellular carcinoma, the expression rate of Derlin-1 was found to be 78.3%." (PMID 35205628, 2022).
ovarian carcinoma (2 papers, 2017 to 2022). A malignant neoplasm originating from the surface ovarian epithelium. "For example, the enhancer at “chr8:124034530-124034920” has the concordant regulatory effects on its target gene DERL1 in 54 TCGA ovarian cancer samples." (PMID 29207666, 2017).
rheumatoid arthritis (2 papers, 2021 to 2024). A chronic, systemic autoimmune disorder characterized by inflammation in the synovial membranes and articular surfaces. "In rheumatoid arthritis patients, the elevated expression of DERL1 correlates with a reduced response to infliximab treatment." (PMID 39040102, 2024).
Alzheimer disease (1 paper, 2023). A progressive, neurodegenerative disease characterized by loss of function and death of nerve cells in several areas of the brain leading to loss of cognitive function such as memory and language. "One study reported that DERL1 colocalized with neurofibrillary tangles in the brain of patients with Alzheimer’s disease and could play an important role in endoplasmic reticulum-associated neurodegeneration." (PMID 37936684, 2023).
breast tumors (1 paper, 2008). "In this study, we detected the expression of derlin-1 in breast tumors and investigated its function in relieving ER stress-induced apoptosis, in order to better understand its role in tumor biology and its potential implication for cancer progression." (PMID 18205950, 2008).
cholera (1 paper, 2019). "The importance of Derlin-1 in CTA transport to the cytosol was further indicated in experiments which demonstrated that suppressing Derlin-1 with siRNA protected cells from cholera intoxication." (PMID 30875878, 2019). "It should be mentioned that experiments in which zebrafish was established as a genetic model for the study of the mechanisms of cholera intoxication, revealed that both, Derlin-1 and -2 are dispensable for retrotranslocation of the CTA1." (PMID 30875878, 2019).
cystic fibrosis (1 paper, 2021). Autosomal recessive disorder caused by pathogenic variants in the CFTR gene (cystic fibrosis transmembrane conductance regulator), which encodes a chloride and bicarbonate channel expressed in epithelial cells, and follow the diagnosis criteria. "Derlin-1 has been implicated in several diseases, such as viral infection, cancer, cystic fibrosis, and neurological dysfunctions." (PMID 34686332, 2021). "Derlin-1 has been previously shown to utilize its rhomboid features for retrotranslocation and is implicated in several pathologies, including cancer, cystic fibrosis, neuropathies, and viral infection." (PMID 34686332, 2021).
Dystonia (1 paper, 2014). An abnormally increased muscular tone that causes fixed abnormal postures. "Protein components of the ERAD pathway, for example, p97 and Derlin-1, as well as torsinA, have been found in inclusion bodies in brain and peripheral nerves from patients with a variety of neurodegenerative diseases, as well as dystonia." (PMID 25379658, 2014).
head and neck cancer (1 paper, 2022). A primary or metastatic malignant neoplasm affecting the head and neck. "In human head and neck cancers, the positive expression rate of Derlin-1 was found to reach 94.7%, and 45.3% of positive tissues showing a high expression level of Derlin-1." (PMID 35205628, 2022).
head and neck squamous cell carcinoma (1 paper, 2021). A squamous cell carcinoma that arises from any of the following anatomic sites: lip and oral cavity, nasal cavity, paranasal sinuses, pharynx, larynx, and salivary glands. "Overexpression of DERL1 is associated with poor survival in head and neck squamous cell carcinoma." (PMID 33946525, 2021).
Huntington disease (1 paper, 2013). Huntington disease (HD) is a rare neurodegenerative disorder of the central nervous system characterized by unwanted choreatic movements, behavioral and psychiatric disturbances and dementia. "The BAD, NEFH, NEFL and DERL1 genes are also involved in Huntington’s disease pathways." (PMID 23782433, 2013).
thyroid cancer (1 paper, 2024). "MDA-T68 cells showed significant upregulation of DERL1 in both thyroid cancer tissues and cell lines." (PMID 38789967, 2024).
uveal melanoma (1 paper, 2025). A melanoma derived from melanocytes of the uveal tract. "Furthermore, within the scope of the same study, a set of genes including DERL1, FBXL17, MBOAT2,PLAG, SLC7A, and YTHDF3 were identified as target genes susceptible to modulation by miR-181b-5p in tumor tissue of uveal melanoma patients." (PMID 38914847, 2025).
Zinc deficiency (1 paper, 2018). A deficiency of the essential metal Zinc; an essential cofactor for many enzymes. "We also found that zinc deficiency caused a conformational change of SOD1WT to a mutant-like form (exposure of the DBR), resulting in SOD1-Derlin-1 interaction." (PMID 29991716, 2018).